TNF (tumor necrosis factor)
Diseases named in the same sentence as TNF in open-access papers (continued):
Sharing a sentence is not in itself a finding about the gene and the disease.
tumor (continued). "In parallel, we found that wild-type Ras (WT-Ras) has cooperated with TNFα, and these two elements together gave rise to the amplified expression and release of CXCL8 by the tumor cells." (PMID 24598028, 2014). "This led to the identification of several pathways that modify tumor growth and invasiveness including the JNK, TNF (Eiger) and JAK/STAT pathways." (PMID 25071815, 2014). "Tumor necrosis factor-α (TNF-α) is one of the most important pro-inflammatory and tumor-related cytokines for its regulating immune response, inflammation, Th1/Th2 balance and lymphomagenesis." (PMID 24857911, 2014). "Pretreatment with IFN-γ and TNF-α induces VEGF expression in MSCs via the HIF-1 α signaling pathway, thereby enhancing the ability of MSCs to promote tumor angiogenesis." (PMID 24502410, 2014). "It is possible that the release of EGF and many other RTK ligands (e.g., VEGF, bFGF, HGF) is induced as a consequence of TNFα activation, leading to RTK activation and then to cooperation in the release of CXCL8 by the tumor cells." (PMID 24598028, 2014). "Because IL-2 can promote the long-term proliferation of T cells, TNF-α and IFN-γ can enhance immunoregulatory ability each other towards anti-tumor." (PMID 25068783, 2014). "Among downregulated proteins, PTEN is a well known tumour suppressor in CRC, while CDC20, TNF and VCAM1 are important protooncogenes." (PMID 25594007, 2014). "Tumor necrosis factor (TNF) and IL-6 were identified as mast cell chemoattractants, which in turn can result in enhanced tumor invasion and metastasis." (PMID 24978438, 2014). "In vivo mouse studies using Lewis lung cancer (LLC) cell lines have shown that tumor infiltrating macrophages have higher IRAK-M expression and impaired ability to secrete IL-12, TNFα, and IFN-γ compared to peritoneal macrophages isolated from the same mouse." (PMID 25452754, 2014). "The tumor-specific angiogenic activity of AITC appears to derive in part from repressing the production of nitric oxide (NO) and tumor necrosis factor-alpha (TNF-alpha)." (PMID 25051185, 2014). "This review surveys the tumor-promoting and tumoricidal activities of several prominent cytokines: IFN-γ, TNF-α, TGF-β, IL-17, IL-23, IL-4, and IL-13, produced by three major subsets of T helper cells that interact with innate immune cells." (PMID 24672527, 2014). "After priming with IFN-γ and TNF-α, the activation of PI3K and p38 MAPK pathways in the neutrophils from tumor-bearing mice and pG/pI6-mice in response to T-sMs was increased to the levels similar to those in the neutrophils from naive mice." (PMID 25587026, 2014). "Consistent with the release of these factors, the cytotoxicity of neutrophils to tumor cells was augmented by priming with IFN-γ and TNF-α." (PMID 25587026, 2014). "Both, tumor and host cells produce different mediators, for example, C-reactive protein (CRP), proinflammatory cytokines with tumor necrosis factor-α (TNF-α), interleukin-6 (IL-6), interferon-γ (IFN-γ), and adipocytokines." (PMID 25049439, 2014). "Perhaps, TNF-α had a protector role in this SCC model, since this cytokine also have been described as involved with anti-tumor immune response in the presence of IL-1β." (PMID 25268644, 2014). "For example, inflammatory mediators TNFα and Interferon γ (IFN γ), as well as tumor-derived proteolytic factors, activate muscle protein degradation, resulting in loss of muscle mass." (PMID 25126097, 2014). "Tumor necrosis factor (TNF)–related apoptosis-inducing ligand (TRAIL), a TNF super family member, induces the apoptosis of virus-infected and tumor cells." (PMID 25196285, 2014). "It has also proved that low levels of TNF-α in the extracellular matrix (ECM) of BC promote the growth and proliferation of tumor cells." (PMID 24864130, 2014).
tumor (continued). "The treatment of mice with NGR–TNF-α, a fusion form of TNF-α with a tumor-homing peptide recognizing specifically TECs, induced intra-tumor upregulation of CAMs, and the infiltration of tumor-specific effector CD8+ T cells." (PMID 24734218, 2014). "Expression levels of GRP splice transcripts were determined in control and cancerous tissues and correlated with gene expression of MGP, GGCX, VKOR, and the tumor markers OPN and TNFα." (PMID 24949434, 2014). "Tumor volumes (tV) were measured daily and tumor weights (tW) on day 15, when study was terminated due to large tumors in LLC+TNF group." (PMID 24664144, 2014). "Compared to non-tumor-bearing controls, mice with LLC had a 443% increase in plasma MCP-1 (p<0.01) and a 397% increase in TNF-α (p<0.01)." (PMID 25356654, 2014). "Moreover, TNF-α may even promote tumor growth at lower levels." (PMID 24676340, 2014). "Tumor tissue was analyzed for relative mRNA expression of a panel of different cytokines (IL1 β, IL2, IL6, IL18, TNF-α and IFN-γ)." (PMID 24676901, 2014). "A third phase II trial looked at DCs loaded with tumor lysate antigens, matured by exposure to prostaglandin E2 (PGE2) and tumor necrosis factor-α (TNF-α), and injected directly into cervical lymph nodes (NCT00323115)." (PMID 24804271, 2014). "Taken together, IL-12 effectively promotes the generation of tumor-specific immune cells co-producing IFN-γ and TNF-α and the response is markedly enhanced when IL-23 is combined with IL-12." (PMID 23844018, 2013). "Adoptively transferred NK cells migrate to tumor sites and directly kill tumor cells, but they also secrete cytokines such as IFN-γ and TNF-α." (PMID 23326467, 2013). "Activated adipocytes, however, produced TNF-α and VEGF, both of which stimulate cell proliferation and supply an energy source for the tumor." (PMID 24015203, 2013). "The previous studies have shown that TNFα down-regulated CFTR mRNA expression in HT-29 cells, a colon epithelium-derived tumor cell line, in a dose- and time-dependent fashion." (PMID 23626828, 2013). "Administration of anti-TNF-α partially abrogated the antitumor activity mediated by the RdB/IL23/p35, whereas anti-IFN-γ completely abolished the tumor regression response." (PMID 23844018, 2013). "Already at the initial phases of the study we found that the combined stimulation had a much higher influence than TNFα alone, estrogen alone, or EGF alone on the tumor-promoting aspects that were studied." (PMID 24369447, 2013). "In fact, either genetic deletion of NF-κB or IL-6, or the inhibition of inflammatory cytokines, such as TNF-α, determined a significant reduction in HCC tumor load." (PMID 23533994, 2013). "Both TNF-α and IL-1β, also found to be upregulated following PTT, can promote tumor growth by inducing IL-6 expression." (PMID 23935927, 2013). "Tumor growth and cytokine responses (IL-1A, MCP-1, TNF-α) were observed for two weeks post-implantation." (PMID 23940596, 2013). "SOCE was not required for the expansion of tumour specific CTLs and their infiltration of tumours, but was necessary for lytic granule exocytosis, tumour cell killing and production of IFN-γ and TNF-α." (PMID 23922331, 2013). "3/8 B6 wild type mice, 1/8 B6.TNF KO mice, and 2/9 B6.TNFR2 KO mice spontaneously rejected the tumor within 14 days." (PMID 24098720, 2013). "In this study the levels of TNF-α, IL-6, COX-2 and VEGF in tumor microenvironment were reduced by virtue of addition of fish oil." (PMID 23349693, 2013). "The induction of T-cell-secreted cytokines, e.g. TNF-α and IFN-γ, further supported its anti-tumor effect." (PMID 24015299, 2013). "Within the tumor microenvironment, COX-2, prostaglandins, SCF, CCL2, GM-CSF, M-CSF, VEGF, CXCL5, calcium-binding pro-inflammatory proteins S100A8 and S100A9, and TNF, all favor the chemotaxis and expansion of immunosuppressive MDSCs." (PMID 23577028, 2013).
tumor (continued). "M2-like TAM have high levels of mannose receptor-1 (MRC1/CD206), arginase-1 (Arg1), IL-10 and chemokines CCL22 and CCL17, whereas anti-tumor M1-like TAM express high interferon (IFN)γ and IL-1α/β levels; TNFα marks both M1- and M2-polarized TAM." (PMID 24317954, 2013). "Because the tumor can be a source or a stimulator of cytokines such as interleukin, IFN-γ, and TNF, this in effect leads to the stimulation of thrombocytopoiesis." (PMID 23554823, 2013). "TAM-derived TNF-α also stimulated the activation of CAF, which are dominant elements in tumor inflammatory milieu, and was involved in promoting Th17 cell expansion." (PMID 23533994, 2013). "The cytokines such as the tumor-necrosis factor (TNF) are produced by immune cells, and can improve the efficacy of the T cell priming and induce adaptive anti-tumor immunity." (PMID 23390614, 2013). "Since previous studies suggested the involvement of isoform shift from 3 to 1 in carcinoma progression, we treated cells with tumor stimulus (TGF-β, EGF and TNF-α) that facilitate the progression and examined the shift." (PMID 23936352, 2013). "Once CD4 T cells are reactivated at the tumour site, their expression of IFN-γ and TNF-α that we measured has multiple potential anti-tumoural consequences." (PMID 23717511, 2013). "Recently it has been also reported that tumor cells treated with TGF-β and TNF-α generates a population of stem cells, further evoking attention on their possible crosstalks." (PMID 23437179, 2013). "The targeted delivery of drug-loaded nanovesicles was examined on the TNF-alpha-treated human umbilical vein endothelial cells (HUVECs) or ICAM-1 expressing HT1080 cells in vitro and mouse CT26 tumour or human A549 tumour-bearing mice in vivo." (PMID 26082317, 2013). "On the other hand, the positive correlation between stromal TNF-α and inflammatory infiltrate, which was more intense in the cases of OSCC, suggests a participation in tumor progression." (PMID 23833665, 2013). "Cytokines including IL-6, VEGF, IGF-1, TNFα, and HGF produced from bone marrow stromal cells (BMSCs) and tumor cells directly and/or indirectly influence MM cells in autocrine and paracrine manners." (PMID 24151609, 2013). "In the nude mice of control (Hep-2/0) group, tumor doubling time was 2.91 days; while in Hep-2/TIC group, Hep-2/CD group and Hep-2/TNF-α group, tumor doubling time was 5.34 days, 4.01 days and 2.99 days, respectively." (PMID 23593411, 2013). "Tumor inhibition rates of Hep-2/TIC group, Hep-2/CD group and Hep-2/TNF-α group were 97.40%, 88.58% and 24.96%, respectively." (PMID 23593411, 2013). "To further evaluate the roles of TNF-α and VEGF for adipocyte activation, we also tested the effect of adding these factors to tumor cells or neutralizing these factors in adipocytes on A549 xenografts." (PMID 24015203, 2013). "In the tumor-free group, the host derived cytokines IL-1β, IFN-γ and TNF-α showed a time-dependent decline in concentration as a consequence of immune cell maturation while IL-17 levels remained stable in function of time." (PMID 24325392, 2013). "As IL-1α, IL-2, IL-6, TNF-α and IFN-γ are the major inflammatory cytokines secreted by immune cells activated by PHA, they are also located in the tumor microenvironment." (PMID 23761816, 2013). "Few years ago, we proposed that delivery of vasoactive inflammatory cytokines like tumor necrosis factor α (TNF) to neo-angiogenic vessels might represent a good strategy to induce selective activation of ECs in tumor tissues, thereby enhancing T cell extravasation and tumor infiltration." (PMID 24062984, 2013). "Subsequently, The TAM will secrete growth factors such as EGF, TGFβ, FGF, VEGF, IL1, TNF and IL6 that promote tumor cell proliferation, invasion and metastasis." (PMID 23874655, 2013).
tumor (continued). "Tumour-secreted factors such as VEGF-A, PlGF, TGF, TNF-a and LOX have been shown to play active roles in the recruitment of bone marrow (BM)-derived cells to the primary tumour microenvironment and pre-metastatic niches." (PMID 26082317, 2013). "Rarely detected in normal TECs, ccRCC, TNF, and TNFR2 protein and mRNA are induced in malignant TECs and infiltrating leukocytes, and TNFR2 increase correlates with malignant/tumor grade." (PMID 24350291, 2013). "Of interest was the fact that due to stimulation by TNFα + Estrogen + EGF, over 50% of the tumor cells acquired high expression levels of both β1 and CD44 together." (PMID 24369447, 2013). "Nizamutdinova and his colleagues have shown that T1 effectively inhibited TNF-α-induced VEGF production and VEGF-mediated tumor formation." (PMID 23662128, 2013). "Immunostaining signal of IL-6, TNFα and VEGF was localized in the cytoplasm of tumor cells and CD34 was localized in endothelial cells of newly formed vessels." (PMID 23688241, 2013). "In the diethylnitrosamine (DEN) model of chemically induced liver carcinogenesis a tumor suppression effect of increased ω-3 PUFA tissue status was demonstrated in the fat-1 mice as well, with lowered plasma TNF-α levels and decreased liver COX-2 expression." (PMID 23691510, 2013). "Exogenous systemic administration of human TNF, however, which only interacts with murine TNFR1, accelerated tumor progression." (PMID 24098720, 2013). "The powerful spreading induced by TNFα + Estrogen + EGF has led us to monitor the expression of the β1 integrin, known to be strongly involved in processes of tumor cell adhesion, spreading, and metastasis formation." (PMID 24369447, 2013). "The TNFα + Estrogen + EGF stimulation has endowed the cancer cells with high spreading and EMT characteristics and with tumor- and metastasis-promoting functions." (PMID 24369447, 2013). "Parthenolide has been found to sensitize tumor cells to cancer drugs, such as tamoxifen paclitaxel and CPT-11 in addition to tumor necrosis factor (TNF), and consequently promote cell death when applied at levels low enough to not be toxic in their own right." (PMID 23783276, 2013). "Since IL-12 and IL-23 can stimulate the production of IFN-γ and TNF-αfrom T and NK cells, we further assessed the expression levels of IFN-γ and TNF-α in the tumor tissues." (PMID 23844018, 2013). "IL-10, along with TNF-α, autocrinally stimulated the expression of B7-H1 on macrophage surface, impairing CD8+ T cell activity and supporting tumor immune escape." (PMID 23533994, 2013). "The HBMSCs preactivated with TNF-α induced apoptosis in MDA-MB231 breast cancer cells, suppressed MDA-MB231 cell cycling, and inhibited the progression of tumours formed from MDA-MB231." (PMID 23815673, 2013). "Thus, new therapeutic strategies to either activate TNFR2 signalling in ACR (to facilitate tubular regeneration) or to selectively inhibit TNFR2 signalling in ccRCC (to halt tumor growth/progression) may be a better approach in the treatment of these conditions than global blockade of TNF." (PMID 24350291, 2013). "Extracellular HMGB1 can induce a variety of cellular responses, including the expression of proinflammatory mediators, such as tumor necrosis factor-α (TNF-α), tumor metastasis, and the maturation of dendritic cells." (PMID 22563397, 2012). "TNF mRNA expression in the SCC tumor center was 515±144-fold higher than in normal skin (p<0.001) and also significantly higher than in the tumor center of BCCs (55.5±29.3, p<0.001)." (PMID 22808251, 2012). "Persistent inflammatory response characterized by activated leukocytes and secretion of several cytokines and chemokines (including tumor necrosis factor (TNF), interleukins, and interferons) elaborates the formation of tumor-promoting microenvironment." (PMID 22482059, 2012).
tumor (continued). "Binding of Prx1 to TLR4 stimulates release of pro-inflammatory cytokines interleukin (IL)-6 and tumor necrosis factor (TNF)-α from macrophages and VEGF from tumor cells, macrophages and endothelial cells." (PMID 23185615, 2012). "TNF-α and IFN-γ were reported to enhance TRAIL-induced cell death of tumor cells and here we have shown that radiation can also enhance TRAIL-induced death, in the absence of such cytokines." (PMID 22389673, 2012). "Even if the locoregional administration of TNF-α by ILP is able to partially attenuate its systemic toxic side effects, the resistance of some tumour cells to the cytotoxic action of TNF-α remains a barrier to its effective application." (PMID 22719951, 2012). "Inhibition of ADAM17 by D1(A12) antibody was expected to inhibit TNF-α secretion and thereby inhibit growth of IGROV1-Luc tumours in vivo." (PMID 22792380, 2012). "Further studies are necessary to understand the greater complexity of TNFα-dependent stimulation of HIF-1α nuclear accumulation and its role in tumorigenesis and tumor progression." (PMID 22355351, 2012). "Tumor-infiltrating mast cells can directly influence proliferation and invasion of tumors, by histamine, IL-8 and VEGF while the production of TNF-α and heparin can suppress tumor growth." (PMID 23217146, 2012). "Interestingly, our own data suggest that low dose, local tumor necrosis factor alpha (TNFα) acts in a similar manner by re-educating macrophages to release inflammatory and angiogenic modulators which in turn remodel blood vessels and support anti-tumor immunity." (PMID 24213314, 2012). "Tumor infiltrating immune cells such as CD4+, CD8+ and FOXP3+ T-cells and macrophages secrete soluble effector molecules such as interferons, IL-6 and TNF, and some of these can directly influence innate immune gene expression in keratinocytes." (PMID 22808251, 2012). "In PGCG, the TNF-α, IL-6 and IL-1β interrelations may control the cellular activities of the different cell populations (multinuclear cells, monocytes/macrophages, spindle fibroblasts/osteoblasts) contributing possibly mainly in the mechanisms of tumor growth, and occasionally of osteolysis." (PMID 22157665, 2012). "We used the specific human TNF-α antibody infliximab in our efficacy studies as a positive control, expecting it to inhibit growth of IGROV1-Luc tumours." (PMID 22792380, 2012). "The results showed that the expression of IFNγ and TNFα in HCC tissues, especially at the edge of tumor, was higher than in normal liver tissues." (PMID 22952657, 2012). "In this study, we first tested three cytokines (TGF-ß, TNF-α, and EGF) for the EMT induction of A549 and Panc-1 cells, analyzing expression of some tumor invasion markers as well as EMT markers." (PMID 23300891, 2012). "For instance, human tumor-infiltrating CD8+/CD28- regulatory T cells secrete IL-10, TNF-α, and IFN-γ, express FOXP3, and suppress the proliferation of CD8+ effector T cells." (PMID 23272178, 2012). "Factors produced by the primary tumor such as VEGF-A, TNFα, and TGFβ also induce expression of the pro-inflammatory cytokines S100A8 and S100A9 in developing pre-metastatic niches in the lung." (PMID 22699312, 2012). "For comparison, a group of mice were treated with infliximab, which was expected to directly reduce functional human TNF-α, also leading to inhibition of growth of the IGROV1-Luc tumours." (PMID 22792380, 2012). "Exogenous treatment with recombinant TNF and IL2 have had success in mitigating tumor progression in a number of diseases." (PMID 22536907, 2012). "Flow cytometry examination revealed that the number of macrophages infiltrated the tumor tissues in the control group, tk or MCP-1 group and tk-MCP-1 group increased in order (P < 0.05), so did TNF-α protein level from the activated microphages." (PMID 22971726, 2012).